IGF2 (insulin like growth factor 2)
Diseases named in the same sentence as IGF2 in open-access papers (continued):
Sharing a sentence is not in itself a finding about the gene and the disease.
depression (continued). "This aspect may be important in establishing peripheral IGF-1 or IGF-2 levels as objective distinguishing biomarkers that can reflect changes in subjective scales of clinical use, such as the Hamilton Depression Rating Scale (HDRS) in the case of depression." (PMID 37894932, 2023). "Therefore, we calculated different linear regression models using the backpropagation methodology to predict the effects of group (control, depression), age (years) and gender (male, female) over the IGF-2 and IGFBP-7 levels." (PMID 37894932, 2023). "Besides, IGF2 also has important effects on multiple brain functions: memory, depression, and autism." (PMID 36673541, 2023). "Decreased levels of a protein upstream of GSK-3, called insulin-like growth factor 2 (IGF2), has previously been implicated in rodent models of depression, with artificial induction of IGF2 expression having protective effects against depressive-like behaviors." (PMID 35546951, 2022). "Moreover, the genes, including Ttr, Prl and Igf2, whose hippocampal expression patterns were downregulated in four rat models of endogenous depression and chronic stress, represent a generalized molecular response to chronic stress." (PMID 24225037, 2013). "In order to immediately address how crucial the role of IGF2 in the development of stress-induced depressive syndrome might be, a chronic intrahippocampal administration of this molecule could be applied with our model." (PMID 22989159, 2012). "Our data suggest that dicholine succinate has an antidepressant-like effect, which might be mediated via the up-regulation of hippocampal expression of IGF2, and implicate the neuronal insulin receptor in the pathogenesis of stress-induced depressive syndrome." (PMID 22989159, 2012). "Another study revealed that the methylation levels of IGF2 DMR were affected by folic acid intake before or during pregnancy and depression in pregnancy." (PMID 25269528, 2014). "In the present study, we found that the levels of IGF-2 were statistically increased in depression when compared to controls, regardless of age and sex." (PMID 37894932, 2023). "Given that IGF-2 can trigger IGF-1R signaling and IGF-2R to act as a memory enhancer, we believe there are reasons to study the possible roles of peripheral levels of IGF-2 and some IGFBPs in the context of depression." (PMID 37894932, 2023). "In our case, we did not measure IGF-1, but we did measure IGF-2, since peripheral IGF-2 has never been measured in the context of human depression." (PMID 37894932, 2023). "Curiously, as far as we have found, no study has yet evaluated either IGF-2 or IGFBP-7 circulating levels in patients diagnosed with bipolar disorder or depression." (PMID 36076984, 2022). "In addition, recent works implicate miR-16-5p, miR-24-3p and miR-146a-5p in the regulation of MAPK downstream BDNF, IGF2 and WNT signaling in depression." (PMID 33546327, 2021). "Hence, this study investigated the hypothesis that prolactin‐induced Igf2 expression in CP tissue during pregnancy and lactation is required for increases in SVZ mitogenesis necessary to alleviate post‐partum anxiety/depression." (PMID 40457890, 2025). "However, to the best of our knowledge, there is no literature available on IGF-2 peripheral levels in major depressive disorders involving human samples." (PMID 37894932, 2023). "The effects of DS parallel a lasting increase of hippocampal expression of IGF2 that is not observed in imipramine-treated mice suggesting distinct mechanisms of beneficial action of the two drugs used here in this model of experimental depression." (PMID 22989159, 2012).
intrauterine growth restriction (29 papers, 2012 to 2025). "Plagl1 was previously shown to regulate expression of Cdkn1c, Igf2, H19, and Dlk1 and to belong to a subset of IGs that control embryonic growth and differentiation, and loss of Plagl1 function resulted in intrauterine growth restriction." (PMID 36437415, 2023). "The imprinted insulin-like growth factor 2 (IGF2) gene has a major role in the matching of placental nutrient supply to fetal demand, and altered IGF2 expression has been reported in association with fetal growth restriction in humans." (PMID 26091021, 2015). "It was reported that IGF2 cord serum concentration had a significant positive effect on both birth length and weight and IGF2 content in the placental lysates was one of the most important factors associated with fetal growth restriction." (PMID 37152930, 2023). "They suggest that poor placentation in fetal growth restriction may be due to deficient microvasculature expansion caused by decreased IGF2 signaling from the fetus." (PMID 36268036, 2022). "Our study aimed to explore whether maternal and paternal factors influence IGF2 polymorphism in intrauterine growth restriction (IUGR) newborns compared to appropriate for gestational age (AGA) newborns." (PMID 35626807, 2022). "This study aimed to explore whether maternal and paternal factors influence IGF2 polymorphism in newborns with intrauterine growth restriction (IUGR) compared to appropriate for gestational age (AGA)." (PMID 35626807, 2022). "Both are involved in regulating conceptus growth and development, with deletion of IGF2R leading to placental and fetal overgrowth, whereas deletion of IGF2 leads to placental and fetal growth restriction, in mice." (PMID 36176700, 2022). "We have previously demonstrated that maternofetal calcium transport, per gram placenta, is increased in the placental specific insulin-like growth factor 2 knockout mouse (P0) model of fetal growth restriction (FGR) compared to wild type littermates (WTL)." (PMID 30515131, 2018). "Low birth weight (LBW), often due to intrauterine growth restriction, may induce epigenetic changes (e.g., IGF2 and PPARG methylation), impairing glucose metabolism and increasing risks of MUHPs (MUHO/MUNW)." (PMID 40662170, 2025). "Future studies may build on the results of this study to elucidate the role that the IGF2 and H19 genes play in the pathophysiology of adverse pregnancy outcomes, for example, intrauterine growth restriction." (PMID 39330587, 2024). "As OLAH protein is low in fetal growth restriction, it is possible that its reduction in disease could decrease IGF2 as well." (PMID 36139751, 2022). "Igf2-null mice display intrauterine growth restriction and placental hypoplasia." (PMID 35741015, 2022). "Placenta targeting nanoparticles carrying insulin-like growth factor 2 (IGF2) improved fetal weight in a model of fetal growth restriction and a selective delivery of nanoparticle carrying nitric oxide releasing drug to uteroplacental vasculature rescued impaired placental perfusion." (PMID 32013041, 2020). "Most defects reported in Igf2 null mice are associated with intrauterine growth restriction and while no testicular defects have been described in Igf2-deficient mice, this does not preclude a putative role of IGF2 in testis development and function." (PMID 25780585, 2014). "In previous studies, it was suggested that the ΔDMR1-U2 knockout mouse showing intrauterine growth restriction was caused by the absence of placenta-specific Igf2 P0 transcription." (PMID 24551836, 2014). "Intrauterine growth restriction and placental hypoplasia in Russell–Silver syndrome are associated with an absence of paternal IGF2 expression, resulting from a loss of methylation of the distal imprinting control region (H19/IGF2:IG-DMR) on 11p15.5 or IGF2 point mutations." (PMID 37764824, 2023).
intrauterine growth restriction (continued). "This study is also in line with the findings of Koukoura and colleagues from Greece who studied 31 placentas with fetal growth restriction (FGR) and found decline in IGF2 mRNA levels and LOI among the abnormal placentas." (PMID 33062920, 2020). "IGF2 expression is additionally modulated by DNA methylation at a number of other DMRs, 15 and altered placental and umbilical cord 5mC at DMRs controlling IGF2 expression has been reported in association with fetal growth restriction in some, but not all15,20 studies." (PMID 26091021, 2015). "Moreover, AGA (appropriate for gestational age) babies had an IGF2 (insulin-like growth factor 2) protective genetic profile (AA genotype) more frequently than IUGR (intrauterine growth restriction) babies, although the threshold of significance was not reached." (PMID 35626807, 2022).
bladder cancer (28 papers, 2000 to 2026). "In the case of IGF2, loss of imprinting allows the transcription of the normally silenced maternal allele, leading to the overexpression of IGF2 in some cancers such as bladder cancer." (PMID 38002994, 2023). "The H19 RNA inhibits insulin-like growth factor 2 (IGF2) transcription and translation, whereas the H19 SNP promotes mitotic IGF2 expression, thereby decreaseing the risk of bladder cancer." (PMID 29299175, 2017). "Decreased DNA methylation at the IGF2/H19 DMR has been associated with reduced IGF2 expression in bladder cancer." (PMID 26115033, 2016). "Two proteins that are overexpressed in bladder cancer are IGF2 and MAGE-A3 can detected by(Immunohistochemistry (IHC) or Western Blotting or Quantitative PCR (qPCR)/RT-PCR)." (PMID 39678505, 2024). "IGF2 mRNA is often upregulated in bladder carcinoma, and a high level of IGF2 protein is present in the urinary samples of bladder carcinoma patients." (PMID 37569864, 2023). "Based on these findings, CRH, ANXA10, and IGF2 were considered bladder carcinoma markers, and were therefore detected in urine samples." (PMID 37569864, 2023). "Linsitinib, an IGF1R inhibitor, was used to block IGF2/IGF1R signaling-mediated AKT phosphorylation in SOX2-expressing bladder cancer cells." (PMID 32427884, 2020). "That is to say, lower expressions of IGF2, GDF15, and KRT13 was associated with lower cell proliferation, invasion, and tumorigenesis of bladder cancer." (PMID 32695477, 2020). "All these data verify SOX2 promotes bladder cancer cell growth and survival by inducing IGF2/IGF1R signaling." (PMID 32427884, 2020). "We examined the relative gene expression levels in the amiRNAs-transfected bladder cancer cell lines and the mRNA levels of c-Myc, cyclin D1, IGF2, and VEGF were down-regulated by the corresponding amiRNA in the bladder cell lines." (PMID 26541358, 2015). "We have shown that IGF2 or H19 are significantly expressed in 50-84% of human bladder carcinomas, respectively." (PMID 21162716, 2010). "IGF2 regulates PI3K/AKT/mTOR signaling pathway, targeting on IGF2 is a new therapeutic strategy for bladder cancer, and obstructing IGF2 signaling way could make cancer cell reacquire sensitivity to Taxol." (PMID 36512456, 2023). "The sixth CTCF-binding site may serve as a significant regulatory domain, thereby switching H19 or IGF2 expression in human bladder cancer." (PMID 34422802, 2021). "The fact that SOX2–IGF2/IGF1R signaling axis confers aggressiveness in bladder cancer suggests that IGF2/IGF1R may serve as therapeutic targets in treating bladder cancer." (PMID 32427884, 2020). "To understand whether IGF2/IGF1R signaling is responsible for high-SOX2 expressing bladder cancer cell growth, we knocked down IGF2 and IGF1R." (PMID 32427884, 2020). "Moreover, we found that SOX2 promotes bladder cancer cell survival by inducing the IGF2/IGF1R pathway, thereby activating AKT survival signaling." (PMID 32427884, 2020). "Since our evidence suggests that SOX2 activates AKT survival signaling and promotes spheroid-forming ability by inducing IGF2/IGF1R in bladder cancer cells, IGF2 and IGF1R may be potential therapeutic targets for treating bladder cancer." (PMID 32427884, 2020). "Our present results confirmed that SOX2 regulates IGF2/IGF1R signaling in bladder cancer cells." (PMID 32427884, 2020). "Patients with bladder cancer also display a significant increase in urinary IGF2 concentration." (PMID 28882129, 2017). "Therefore, we further investigated the combination use of H19 and IGF2 regulatory sequences for driving toxin gene expression in therapeutic vectors for bladder cancer treatment." (PMID 21162716, 2010). "In addition, abnormal signal transduction and/or promoter activation was reported as a major mechanism for the IGF2 overexpression in a variety of tumors including bladder carcinoma, hepatocellular carcinoma, breast cancer, ovarian cancer and prostate cancer." (PMID 21162716, 2010).
bladder cancer (continued). "Since SOX2 mediates stem cell differentiation and iPSC reprogramming mainly via epigenetic regulation, whereby H3K4me3 marks sites with active gene expression, we examined whether H3K4me3 signal on the IGF2 locus is affected by SOX2 expression in bladder cancer cells." (PMID 32427884, 2020). "The XPERT© Bladder Cancer Monitor is a test for detecting the five mRNA sequences (ABL1, CRH, IGF2, UPK1B, ANXA10) in urine." (PMID 35804953, 2022). "H19 promoter region can bind to CCCTC-binding factor (CTCF) and insulin like growth factor 2 (IGF2), and thereby regulating bladder cancer development in nucleus of BC cells." (PMID 34422802, 2021). "Based on the detection of five mRNA targets in urine (CRH, IGF2, UPK1B, ANXA10, and ABL1), Xpert Bladder Cancer (Xpert BC) is a recently developed detector for the detection of bladder cancer, which is non-invasive and highly economical." (PMID 33563292, 2021). "In conclusion, we demonstrated that SOX2 stimulated IGF2 expression to activate AKT signaling, enhancing the survival and spheroid-forming capability of bladder cancer cells." (PMID 32427884, 2020). "This suggests that IGF2 and IGF1R are crucial for SOX2-mediated growth and survival of bladder cancer cells." (PMID 32427884, 2020). "Fetal hepatocytes have high IGF2 and E2F3 expressions, and levels of IGF2 and E2F3 mRNA were positively correlated to human prostate and bladder cancers." (PMID 25580437, 2014). "Hence, our findings that SOX2 activates IGF2/IGF1R signaling and predicts poor prognosis further link IGF2/IGF1R signaling to SOX2 mediated aggressiveness in bladder cancer." (PMID 32427884, 2020). "Knockdown of IGF2 and IGF1R attenuated the growth of bladder cancer cells." (PMID 32427884, 2020). "Furthermore, we identified IGF2 and IGF1R as AKT upstream molecules which induce AKT phosphorylation in SOX2-positive bladder cancer cells." (PMID 32427884, 2020). "Although IGF2/IGF1R signaling enhances tumor progression in several cancers, it is unclear whether IGF2/IGF1R signaling contributes to bladder cancer progression." (PMID 32427884, 2020). "Indeed, we found that pharmacological inhibition of IGF2/IGF1R signaling with linsitinib decreased AKT phosphorylation and attenuated bladder cancer cells’ SOX2-mediated colony-forming ability." (PMID 32427884, 2020). "Promising pathways for early detection, diagnosis, and prognosis of bladder cancer are provided by these biomarkers, which include the UBC® Rapid test, UBC ELISA kit, Xpert® Bladder Cancer Monitor, BC UroMark, TaqMan® Arrays, Soluble FAS (sFAS), Bladder tumor fibronectin (BTF), and IGF2 and MAGE-A3." (PMID 39678505, 2024). "Moreover, knocking down IGF2 and IGF1R diminished bladder cancer cell growth." (PMID 32427884, 2020).
pancreatic cancer (28 papers, 2007 to 2024). "In pancreatic cancer, deregulation of IGF2 has also been shown to be associated with beta-cell tumorigenesis, and pancreatoblastoma is associated with chromosome 11p loss of heterozygosity and IGF2 overexpression." (PMID 27895308, 2016). "MiR-663b has been described as a tumor suppressor in pancreatic cancer cells, able to repress IGF2 expression via targeting of its 3’UTR, thereby suppressing cell proliferation." (PMID 33540611, 2021). "For instance, in vivo studies have noted that the inhibition of IGF-1/IGF-2 sensitized pancreatic tumors to gemcitabine, whereas combined IGF-1R and CSF-1R inhibition significantly improved survival outcomes in mice with glioblastoma multiforme." (PMID 32512898, 2020). "A previous study showed that miR-663b exerted its tumor-suppressive function via targeting insulin-like growth factor 2 in pancreatic cancer." (PMID 31844676, 2019). "Insulin-like growth factor 2 (IGF2) mRNA binding proteins (IGF2BPs/IMPs) have been described to be oncogenic in several types of cancer including pancreatic cancer." (PMID 31261900, 2019). "In a similar fashion, HOTAIR epigenetically silences miR-663b to upregulate its target IGF2 (insulin like growth factor 2) and promote pancreatic cancer growth." (PMID 29702599, 2018). "In vitro mechanistic studies revealed the tumor suppressive role of miR-663b via targeting IGF2 in pancreatic cancer, and further study showed that HOTAIR-mediated down-regulation of miR-663b was via regulating histone modification." (PMID 27895308, 2016). "In summary, our studies demonstrated that miR-663b is epigenetically repressed by HOTAIR and exerts its tumor-suppressive function via targeting IGF2 in pancreatic cancer." (PMID 27895308, 2016). "In the clinical samples, IGF2 was up-regulated in pancreatic cancer tissues, and miR-663b level was inversely correlated with IGF2 level in the pancreatic cancer." (PMID 27895308, 2016). "Luciferase reporter assay and rescue experiment confirmed that miR-663b targets 3’UTR of IGF2 to suppress the expression of IGF2 and inhibits pancreatic cancer cell proliferation." (PMID 27895308, 2016). "Pearson's correlation analysis showed that miR-663b levels was inversely correlated with IGF2 level in pancreatic cancer tissues." (PMID 27895308, 2016). "Further, our previous study showed that IGF2 was down-regulated in pancreatic cancer tissues and was a direct target of miR-615-5p." (PMID 27895308, 2016). "Results from clinical samples showed that the expression level of miR-663b correlated with the pathological grading, and the expression of miR-663b was down-regulated and was inversely correlated with IGF2 expression level in pancreatic cancer tissues." (PMID 27895308, 2016). "In vitro mechanistic studies have revealed that miR-663b activity can be blocked by its interaction with HOTAIR, suggesting that miR-663b is epigenetically repressed by HOTAIR and exerts its tumor suppressive function via targeting of IGF2 in pancreatic cancer." (PMID 33540611, 2021). "For instance IGF2–IGFBP complexes have been found accumulated in pancreatic cancer." (PMID 32934005, 2020). "For example, CAFs produce an abundance of insulin-like growth factor 2 (IGF2) that renders cholangiocarcinoma and pancreatic cancer cells resistant to EGFR tyrosine kinase inhibitors (TKI) by activating the insulin receptor (IR)/insulin-like growth factor 1 receptor (IGF1R) signaling axis." (PMID 31067787, 2019). "ASPC is a pancreatic cancer cell line that was previously shown to maintain IGF2 imprinting." (PMID 27275535, 2016). "This 3-gene predictive biomarker (TGFB3, IGF2, and SMO) was found to correlate with tumor growth inhibition in preclinical patient-derived pancreatic cancer xenograft models." (PMID 31338636, 2020). "However, the role of IGF2 in pancreatic cancer remains unclear." (PMID 27895308, 2016).